BDNF (brain derived neurotrophic factor)
Diseases named in the same sentence as BDNF in open-access papers (continued):
Sharing a sentence is not in itself a finding about the gene and the disease.
Stroke (continued). "In Met allele carriers, if silent axons are less likely to be pruned due to reduced BDNF secretion, structural connectivity might be less profoundly shaped by stroke than in Val homozygotes." (PMID 33029116, 2020). "It was concluded that frequentlower intensity exercise, such as provided by voluntary running wheels, is safer forrats with stroke, and has a delayed but sustained effect on BDNF that may supportbrain remodeling after stroke." (PMID 32555931, 2020). "BDNF plays a significant role in the prognosis, pathogenesis, and rehabilitation of stroke." (PMID 32399020, 2020). "This preliminary study deserves more investigation to confirm if BDNF rs6265 SNP and its methylation could be used as a biological marker of recovery in patients with stroke undergoing rehabilitation treatment." (PMID 33182716, 2020). "Neurotrophic factors from NGF (nerve growth factor), GDNF (glial cell-derived neurotrophic factor), and BDNF (brain-derived neurotrophic factor) may attenuate the neurotoxic inflammatory response after a stroke." (PMID 33042113, 2020). "Polymorphisms in a number of candidate genes, such as IL-6, BDNF, COX2, CYPC19, and GPIIIa could be associated with stroke outcome and recovery." (PMID 33049931, 2020). "BDNF expression could be significantly and obviously induced in the hippocampus and cortex areas of the left cerebral hemisphere from recurrent stroke mice after LIPUS treatment." (PMID 31635269, 2019). "In addition, aged stroke mice treated with the BDNF decoy, TrkB-Fc, blocked the stroke-induced improvement in cognitive flexibility." (PMID 31191635, 2019). "However, other studies rejected BDNF involvement in post‐stroke recovery, a likely explanation being pathological downregulation of BDNF receptors." (PMID 31273936, 2019). "Importantly, several studies have also reported that a critical threshold in BDNF activity is required in order to achieve an improvement in functional recovery in the weeks following stroke." (PMID 31427916, 2019). "In this study, we hypothesized that consecutive LIPUS treatment possessed ameliorated effects on stroke recurrence via BDNF induction." (PMID 31635269, 2019). "Several studies documented neurotropic actions of T3 that can be potentially neuroprotective under stroke, including reduction of developmental neuronal apoptosis, decreased glutamate transfer into brain cell and increased brain-derived neurotrophic factor (BDNF)." (PMID 31690277, 2019). "Another challenge to the use of BDNF in brain therapy is aberrant function of TrkB‐FL receptor, already described in stroke and other disorders, which might be prevented by neuroprotective peptide TFL457." (PMID 31273936, 2019). "Furthermore, BDNF expression levels have been found to be higher in the healthy group than in the stroke patient group, who are unable to exercise." (PMID 32018343, 2019). "The induction of BDNF may play an important role in the improvement of stroke and its recurrence after LIPUS treatment." (PMID 31635269, 2019). "We next investigated whether LIPUS administration could improve the stroke recurrence through the induction of BDNF." (PMID 31635269, 2019). "Interestingly, aged stroke animals outperformed their sham counterparts, suggesting reopening of a critical window for recovery that is being mediated by BDNF." (PMID 31191635, 2019). "Another study on human ischaemic stroke demonstrated that there is an increase in BDNF+ Treg cells in stroke patients compared to healthy controls, and that those stroke patients with higher percentages of BDNF+ Treg in their serum had a better neurological outcome 6 months post-stroke." (PMID 31572381, 2019). "We hope this may be able to “tap into” this BDNF-mediated mechanism to further promote recovery after stroke." (PMID 31191635, 2019). "Finally, we demonstrate that stroke to the PFC of aged mice reopens a critical window for functional recovery that is BDNF dependent." (PMID 31191635, 2019).
Stroke (continued). "Moreover, activity-driven increases in BDNF have also been shown to promote motor recovery after stroke." (PMID 31427916, 2019). "It remains to be determined whether elevated BDNF levels contribute to motor reorganization and stroke recovery." (PMID 30983963, 2019). "Supporting this, systemic administration of the high impact AMPAKine (positive allosteric modulator of AMPA receptors), CX1837, has been reported to stimulate an increase in BDNF expression and promote functional recovery in aged mice following photothrombotic strokes." (PMID 31427916, 2019). "In response to the stroke stress, many cytokines such as brain-derived neurotrophic factor (BDNF), vascular endothelial growth factor (VEGF), insulin-like growth factor-1, and fibroblast growth factor-2 participate in proliferation of progenitor cells in both the SVZ and SGZ." (PMID 31191223, 2019). "A resulting 19–30% reduction in activity-dependent secretion of BDNF protein has been reported in humans carrying this SNP, with worse functional outcomes being reported in these individuals following a stroke." (PMID 31427916, 2019). "Therefore, further investigation is needed in order to clarify the role of BDNF in aerobic exercise applied as a “priming” before or after motor learning task post-stroke." (PMID 30210424, 2018). "In addition, more evidence is needed regarding systemic BDNF responses to exercise comparing the different phases of post-stroke recovery, such as acute, sub-acute and chronic phases." (PMID 30210424, 2018). "The role of BDNF after stroke has been highlighted in many studies." (PMID 30210424, 2018). "Only one study evaluated systemic BDNF concentration following aerobic exercise training in humans post-stroke, while all others evaluated central BDNF concentration in animal models of stroke." (PMID 30210424, 2018). "BDNF has a major role in spontaneous and rehabilitation-induced recovery following stroke." (PMID 30050416, 2018). "The time post-experimental stroke when the BDNF concentrations were evaluated varied among studies as well, which could be another source of disagreement between results." (PMID 30210424, 2018). "In the present study, we confirmed the effects of TST and inhibition of contralesional DNA methylation on functional outcome, neuronal plasticity, and expression of axonal-growth-enhancing molecules (such as BDNF) in the chronic stage after stroke in a rat model." (PMID 29997355, 2018). "Therefore, the follow-up assessments for depressive mood at the chronic stroke phase are needed to clarify the role of serum mature BDNF in PSD." (PMID 30322026, 2018). "For instance, during the recovery period from stroke, physical activity alone is considered an essential factor for improving motor functions, and this conclusion is confirmed through measurement of the brain-derived neurotrophic factor (BDNF)." (PMID 30405992, 2018). "BDNF is crucial for exercise learning and systemic rehabilitation after stroke." (PMID 29899693, 2018). "Intravenous BDNF delivery enhances post-stroke sensorimotor recovery and stimulates neurogenesis." (PMID 30217051, 2018). "Therefore, the training parameters and effort levels should be addressed in future studies in subjects post-stroke to identify the most appropriate training parameters that would result in increased levels of BDNF." (PMID 30210424, 2018). "However, conclusions regarding the most effective aerobic training parameters for increasing BDNF concentrations are still limited post-stroke, given the large heterogeneity across studies available in the literature." (PMID 30210424, 2018). "We determined that BDNF is significantly and continuously released from a fully gelated hydrogel to the surrounding tissue over a period of three weeks after implantation in our animal stroke model." (PMID 30486515, 2018).
Stroke (continued). "Knowledge that BDNF promotes CNS myelination through TrkB signalling suggests it could be targeted as a therapeutic for demyelinating conditions, including stroke, traumatic injury and multiple sclerosis (MS)." (PMID 30572673, 2018). "BDNF/TrkB signaling and TrkB-FL/TrkB-T1 balance are two targets for stroke therapies." (PMID 30809253, 2018). "Thus, the primary objective of this study was to carry out a systematic review of literature investigating the effects of aerobic exercise and functional task training on BDNF concentrations in animals or humans post-stroke." (PMID 30210424, 2018). "Although our results demonstrated that BDNF/TrkB pathway plays an important role in remyelination during NAM treatment after stroke, it is unknown how NAM enhanced BDNF expression after stroke." (PMID 28656112, 2017). "This relationship irisin precursor, namely, FNDC5, and BDNF may be of fundamental importance in the comprehension of the role of training in stroke, particularly because physical exercise induces BDNF but also synapsin I in the hippocampal trisynaptic circuit." (PMID 28373915, 2017). "Although BDNF has been widely investigated, the mechanism of action and the biological correlates of cognitive rehabilitation in patients with stroke are still unknown." (PMID 28859664, 2017). "The disorders and pathological conditions induced or promoted by aberrant BDNF/TrkB signalling could be potentially treated by fine-tuned activation (e.g., stroke, neurodegenerative diseases) or suppression (e.g., epilepsy, cancer) of this pathway." (PMID 28134845, 2017). "Heightened expression of BDNF plays an important role in modulating neurogenesis after stroke." (PMID 28056920, 2017). "We hypothesized that the reduction of lactate or BDNF expression by AVP might be related to the induction of stroke in the SHRSP/Izm rat strain." (PMID 28865453, 2017). "Nicotinamide administration improves remyelination after stroke via the NAD+/BDNF/TrkB pathway." (PMID 28656112, 2017). "Following stroke, the temporal and spatial expression of BDNF has been studied." (PMID 28640888, 2017). "Therefore, our results suggest that NAM administration enhanced BDNF expression via increased NAD+ level after stroke induction." (PMID 28656112, 2017). "In conjunction with these neuroprotective effects, protein expression levels of BDNF and TrkB activation (phosphorylated-TrkB) were significantly increased by high-frequency rTMS, indicating that this approach is a promising strategy for stroke rehabilitation." (PMID 28230741, 2017). "A variety of neurotrophic factors, including BDNF, have been reported to promote the survivals of neurons in culture and to protect against excitotoxic or neurotoxin-induced lesions in animal models of stroke or Parkinson’s disease." (PMID 28886144, 2017). "We showed that NAM administration could promote remyelination after stroke via a NAD+/BDNF/TrkB pathway." (PMID 28656112, 2017). "It is still unknown, whether eNOS is involved in ARB-induced BDNF expression in hypertensive animals after stroke." (PMID 28640888, 2017). "To determine whether BDNF/TrkB pathway plays a role in the remyelination process during stroke recovery, we tested the effect of ANA-12, a selective TrkB antagonist." (PMID 28656112, 2017). "To determine whether NAM-induced NAD+ elevation affects BDNF expression after stroke, we assessed expression of BDNF in the peri-infarct area of the brain." (PMID 28656112, 2017). "Nonetheless, our results demonstrate that rTMS combined with rehabilitation improves motor function in the affected limb after stroke irrespective of BDNF gene polymorphism." (PMID 27007747, 2016). "Furthermore, exogenous administration of GDNF and BDNF reduced the toxic effects of excitatory amino acids, attenuated nitric oxide production, and lowered apoptosis/cell death in stroke animal models." (PMID 26706245, 2016).
Stroke (continued). "Additionally, Fouda and colleagues found knockdown BDNF in animal stroke model notably decrease cerebral vascular density, and it suggested BDNF also had important angiogenic function." (PMID 27465579, 2016). "Administration of BDNF via the intravenous route as well as the intracerebroventricular route reduced infarct size and improved outcome in the transient middle cerebral artery occlusion model of stroke." (PMID 25789320, 2015). "Of the known gene targets of ALA, BDNF shows promise as a therapy for stroke." (PMID 25789320, 2015). "Thus, the objective of our study was to investigate the impact of rt-PA treatment on post-stroke circulating BDNF levels in humans and in animals." (PMID 26469350, 2015). "However, circulating BDNF levels at both the acute (day 1) and chronic (3–6 months) stages of stroke were lower in patients with post-stroke depression (PSD) than in non-PSD patients." (PMID 26469350, 2015). "Correlations between serum BDNF and t-PA/plasmin activity in stroke patients." (PMID 26469350, 2015). "Overall, the data suggest that serum BDNF levels may not be useful as a prognostic biomarker of stroke outcome and that endothelial dysfunction could be a confounding factor when serum BDNF levels after stroke are used to reflect of brain BDNF levels." (PMID 26469350, 2015). "From these data, serum BDNF levels were expected to mirror brain BDNF levels after stroke." (PMID 26469350, 2015). "Correlations between serum BDNF levels and t-PA/plasmin activity in stroke rats." (PMID 26469350, 2015). "Correlation between serum BDNF and cardiovascular score in stroke patients." (PMID 26469350, 2015). "Circulating BDNF levels in stroke patients are poorly documented." (PMID 26469350, 2015). "Growths factors have been applied in stroke regeneration such as BDNF, GDNF and EPO." (PMID 25984331, 2014). "Moreover, GIG training improves BDNF production in brain tissues after stroke, indicating better brain function recovery." (PMID 25045713, 2014). "Thus, cbMNCs and, to a lesser extent, cb/cmMSCs, possibly restore the stroke-induced depletion of endogenous BDNF." (PMID 24690461, 2014). "Interestingly, disrupting the expression of BDNF after focal stroke prevented training-induced recovery of skilled reaching in rats." (PMID 24914807, 2014). "Other studies have shown that rotarod exercise combined with S-nitrosoglutathione (GSNO) can stimulate the expression of neurorepair mediators, such as BDNF and its receptor, tropomyosin receptor kinase B (TrkB) in a stroke rat model induced by middle cerebral artery occlusion." (PMID 24566146, 2014). "We also analyzed CORT and BDNF levels in early stroke phase." (PMID 25045713, 2014). "Our in vitro data also support the hypothesis that the increased WM damage post-stroke observed in eNOS-/- mice is at least partially, mediated by decreasing BDNF/TrkB signaling activity." (PMID 24236179, 2013). "In an experimental stroke model, intranasal BDNF was shown to modulate local inflammation and protect against cerebral ischemia by upregulating anti-inflammatory cytokine IL-10, down-regulating the pro-inflammatory cytokine TNF-α, and in turn increasing the DNA-binding activity of NFKB." (PMID 23912236, 2013). "BDNF interaction with tropomyosin-related kinase B receptors and presynaptic muscarinic receptors modulates transmitter release in adult rodent motor nerve terminal, which can improve stroke motor function recovery." (PMID 24194776, 2013). "Limited reports indirectly support the effect of BDNF on SVZ cell migration in stroke animals." (PMID 24312581, 2013). "It thus appears that the release of both pro-inflammatory cytokines and BDNF may be transiently enhanced after stroke, possibly to protect damaged neuronal tissue." (PMID 23675319, 2013).
Stroke (continued). "This may reflect a need for sustained delivery and transport of BDNF into the CNS parenchyma, as either stem cell-mediated delivery, or systemic delivery of BDNF conjugated to a BBB transferrin receptor antibody reduced stroke injury." (PMID 23613937, 2013). "Indirect evidence supports that BDNF has neuroreparative effects via SVZ in stroke animals." (PMID 24312581, 2013). "The role of BDNF in NPCs after stroke is still not fully understood." (PMID 24312581, 2013). "Regional manipulation of BDNF expression through AAV may be a novel approach for neurorepair in stroke brains." (PMID 24312581, 2013). "However, since BDNF is a secreted protein that can be sequestered by other cell types, a detailed analysis of BDNF mRNA expression in post-stroke areas is required to determine its cellular source." (PMID 23383048, 2013). "In this study, we demonstrated a neuroregenerative effect of BDNF after stroke." (PMID 24312581, 2013). "Our data show that eNOS plays a critical role in WM-damage after stroke, and eNOS-/--induced decreases in the BDNF/TrkB pathway may contribute to increased WM-damage, and thereby decrease functional outcome." (PMID 24236179, 2013). "Comparisons of BDNF immunostaining between sedentary and exercised stroke rats in cortical regions outside the lesion showed that exercise induced an increase in neuronal staining (F1 vs F2) and the appearance of a strong BDNF staining of cerebral endothelium (G1 vs G2)." (PMID 22962604, 2012). "Therefore, the present study compared the effects of a clinically-relevant form of exercise on cerebral BDNF levels and localization in control versus stroke rats." (PMID 22962604, 2012). "At this delayed stage of stroke, intense BDNF staining was observed in neurons and astrocytes, suggesting that the two types of cells contribute to long-term adaptive changes that were reported in stroke animals and patients." (PMID 22962604, 2012). "CpG methylation status at promoter regions on the BDNF gene may influence stroke outcomes, since it also regulates BDNF release, and so we took the opportunity to test the hypothesis within a defined post-stroke cohort." (PMID 23240009, 2012). "BDNF has shown early genomic response following ischemic injury in rat brain, and therefore the influence of BDNF genotype on BDNF secretion might be initiated at the acute phase of stroke." (PMID 23240009, 2012). "These are consistent with recent findings that BDNF methylation is associated with memory consolidation and exercise related neuronal plasticity in rats, although these were not stroke models." (PMID 23240009, 2012). "The DNA promoter methylation profile of the BDNF might be a prognostic biomarker for long-term stroke outcomes." (PMID 23240009, 2012). "Development of a new drug, which could increase BDNF release and regulate BDNF promoter methylation, may be helpful for enhancing stroke recovery." (PMID 23240009, 2012). "Notably, the fact that exercise increased mBDNF in the cortex but not in subcortical regions supports the notion that the therapeutic efficacy of treadmill exercise after stroke is related to BDNF-dependent plasticity in this region." (PMID 22962604, 2012). "Moreover, these grafted neural stem cells modified by the GDNF gene had higher survival rates and differentiation after stroke, less apoptosis, and greater expression of BDNF and NT-3." (PMID 23251608, 2012). "Brain BDNF levels measured in selected embolized rats were compared to those measured in control rats (no surgical procedure but anaesthesia and blood collection were on the model of group “stroke 8 d”, n = 7)." (PMID 22195050, 2011). "In conclusion, stroke increases BDNF levels in the whole brain but not in the blood, and high plasma BDNF levels in the very acute stage are associated with severe stroke." (PMID 22195050, 2011). "However, a positive correlation was observed between plasma BDNF levels at 4 h post-embolization and stroke severity (n = 10, rs = 0.673, p = 0.019)." (PMID 22195050, 2011).